IL6 (interleukin 6)
Diseases named in the same sentence as IL6 in open-access papers (continued):
Sharing a sentence is not in itself a finding about the gene and the disease.
infection (continued). "We also tested whether mAb neutralization affected C. difficile colonization burden in stool and measured pro-inflammatory chemokine CXCL1/KC and cytokine IL-6 levels in blood serum and cecum/colon tissues to assess local and systemic responses to infection." (PMID 41183070, 2025). "Furthermore, XY018 treatment reduced inflammatory cell infiltration and decreased viral mRNA levels, as well as TNF-α, IL-1β, and IL-6 mRNA levels in the lung tissues of H5N1 virus-infected mice on day 3 after infection." (PMID 41134862, 2025). "For instance, it may inhibit the release of proinflammatory cytokines such as Tumor Necrosis Factor-alpha (TNF-α), Interleukin- beta (IL- β), and Interleukin-6 (IL-6), which are known to promote hormonal disruption and tissue damage during infection." (PMID 41400854, 2025). "Additionally, in the immune response, pro-inflammatory factors such as IL-6 and IL-1β recruit immune cells to the infection or injury site to promote inflammation." (PMID 39670511, 2025). "A slight increase in our patients could also suggest a persistent infection because, in the case of IL-6, its importance in the defense against infection is emphasized." (PMID 40647668, 2025). "However, IL-6 secretion was significantly enhanced in primed BMCs derived from old PA-fed animals following infection." (PMID 40581654, 2025). "Moreover, it has been shown that the initial production of IL-6 in response to infection is necessary for the host organism to respond appropriately to the immune system." (PMID 40647668, 2025). "Constantly elevated TNF-alpha, IL-1 beta, IL-1 alpha, IFN gamma, and IL-6 levels throughout infection with both viruses might be linked to sustained apoptosis." (PMID 40358160, 2025). "Clinically, higher IL-6 levels in airways or serum often correlate with more severe disease, such as the need for ventilation or greater hypoxemia although IL-6 can also play a protective role by recruiting immune cells to clear infection." (PMID 40630640, 2025). "However, the IL-6 level in the attenuated mutant group was found to be higher than that in the rVSV-WT group at 4 h post-infection, but was lower at 24 h post-infection." (PMID 40872776, 2025). "Furthermore, inflammation, infection, and acute stress trigger rapid increases in the circulating IL-6 concentration and induce a fever response by promoting PGE2 synthesis." (PMID 41143503, 2025). "GrzmK also induces a pro-inflammatory immune response by stimulating the release of IL-1β, IL-6, and IL-8 by macrophages, fibroblasts, epithelial cells, and endothelial cells to take care of the infection by promoting immune cell infiltration and their pro-inflammatory actions." (PMID 41009359, 2025). "Very low levels of IL-6 are sufficient to enhance fibrinogen transcription in hepatocytes, supporting a transient increase in fibrinogen during acute tissue injury or infection." (PMID 41157266, 2025). "While IL-6 is a typical pro-inflammatory cytokine, its role during Mtb infection is complex, as both protective and detrimental effects have been reported depending on the infection context." (PMID 41492386, 2025). "Serum levels of IL-6 were elevated at 70 dpi (P=0.0132 vs 0 dpi), following a gradual decline towards 365 dpi, consistent with the recruitment of neutrophils to the site of infection, reminiscent of an acute inflammatory pattern." (PMID 40809173, 2025). "Furthermore, analysis of serum inflammatory cytokines indicated that montelukast effectively suppressed the secretion of pro-inflammatory mediators such as TNF-α and IL-6, suggesting a dual role in infection control and inflammation modulation." (PMID 41090944, 2025). "The elevation of IL-6 and IL-1β further supports this, as these cytokines are essential for initiating effective inflammatory responses and recruiting immune cells to sites of infection." (PMID 40969767, 2025). "Interleukin 6 is produced early after infection as part of the induced innate immune response." (PMID 40934714, 2025).
infection (continued). "In a murine model of MRSA-induced PJI, VZZ-8 NPs exhibited robust antibacterial efficacy, concurrently suppressing local TNF-α and IL-6 expression, and preventing infection-induced osteolysis, highlighting their comprehensive therapeutic potential for PJI treatment." (PMID 41305340, 2025). "This study aims to examine the peripheral blood levels of TNF-α, IL-6, and IFN-γ in DFI patients and analyze their relationship with infection severity and prognosis, thereby offering diagnostic evidence for the early identification and personalized treatment of DFI." (PMID 40677522, 2025). "Moreover, PEGylated phages effectively suppressed infection-driven cytokines, reducing IL-6, TNF-α, IFN-γ, and IL-1β levels toward baseline while inducing weaker IgG responses." (PMID 41309396, 2025). "Additionally, upregulation of the IL-6 gene was detected in vPdR-H30K-5U-infected cells, which is consistent with the high IL-6 RNA levels observed after the infection of pigs with a highly virulent CSFV strain." (PMID 40006915, 2025). "Of particular interest is research using selective IL-6 inhibitors that aim to not increase the risk of infection." (PMID 39857830, 2025). "Finally, these reversed M‐BMMCs produced more than fivefold higher levels of secreted IL‐6 upon infection with invasive S.Tmwt." (PMID 40838737, 2025). "IL-6 plays a key role in host defense against pathogens, injury, and infection." (PMID 40573262, 2025). "In this study, the infection rate in the intravenous group was 10%, and infection-related inflammatory factors (such as IL-6) could interfere with insulin signaling pathways, exacerbating blood glucose fluctuations." (PMID 40585912, 2025). "Interestingly, probiotic CFSs and vitamin D differentially reduced the infected cell IL-6 production and counteracted the infection-induced cytotoxicity." (PMID 40351306, 2025). "Notably, the infection-induced levels of pro-inflammatory cytokines IL-6 and TNF-α decreased time-dependently (solid lines), whereas for uninfected wounds, the levels of TNF-α significantly increased over time (dashed lines)." (PMID 40630479, 2025). "Similarly, at 12h post-infection, FH-treated cells showed decreased mRNA levels of IL-6 [~ -1.2 log10], IFN-α [~ -1.9 log10]), IL-1β [~ -2.7 log10], and IFN-α [~ -2.9 log10], RANTES [~ -0.8 log10], and IL-8 [~ -2.1 log10] compared to untreated cells." (PMID 40895576, 2025). "Given the timing of peak concentrations of IL-6 relative to CRP, there might be an advantage in infection risk prediction for IL-6 when assessing infection risk directly postoperative." (PMID 40549692, 2025). "In addition, in vitro studies using a human blood-brain barrier (BBB) model showed that USUV infection leads to upregulation and release of inflammatory cytokines such as IL-6, TNF-α, and IL-1β, both on the apical and basolateral sides of the barrier." (PMID 40731345, 2025). "High IL-6 levels In critically ill patients are Indicative of ongoing Inflammation and are associated with poor clinical outcomes, Including prolonged ICU stays and Increased risk of Infections like VAP." (PMID 40951884, 2025). "It was found that SIRT7-KO cells showed less cell damage infection, and significantly reduced expression of pro-inflammatory cytokines (IL-6, IL-8, TNF-α) upon GPS infection, suggesting that SIRT7 deficiency can suppress the occurrence of inflammation induced by GPS infection." (PMID 40636259, 2025). "Conversely, at 72 hours post-infection, the secretion of IL-6, IL-17, T-bet, TNF-α, and IFN-γ was significantly diminished (P < 0.01), while levels of TGF-β, GATA-3, IL-10, and IL-4 were significantly elevated in the Pm_OMVs-infected group compared to the Pm group (P < 0.01)." (PMID 41306977, 2025). "Interleukin-6 levels were elevated in 11 patients (61%), indicating ongoing infection." (PMID 40566535, 2025). "Diagnostic value of serum TNF-α, IL-6, and IFN-γ in assessing the severity of infection." (PMID 40677522, 2025).
infection (continued). "Given that these oral pathogens infect both the oral mucosa and the pharynx, and that FaDu cells express key receptors like IL-6, they are suitable for evaluating the effect of probiotic CFSs and vitamin D during infection extending beyond the oral cavity, ensuring reproducible results." (PMID 40351306, 2025). "The ability of IL-6 to provide insights into both infection and systemic inflammation makes it a valuable tool for guiding clinical decision making in HTx patients, particularly in the context of the complex interplay between infection, inflammation, and immunosuppression." (PMID 40806991, 2025). "IL-6 is an important mediator of fever, a critical infection defense mechanism in young animals." (PMID 41375563, 2025). "This elevation may enhance the host cell’s ability to mount an effective defence against T. gondii, as previous studies have shown that IL-6 plays a protective role during infection by promoting localised inflammation and maintenance of pregnancy." (PMID 41011132, 2025). "All the data obtained by us, corroborated with those from the scientific literature, entitle us to hypothesize that the causal element of these behaviors is genetically conditioned IL-6 overproduction (possibly acquired post-infection)." (PMID 40283387, 2025). "In contrast, Presepsin and IL-6 have proven to be reliable early markers of infection." (PMID 40806991, 2025). "The primary infection of either organism may lead to chronically elevated levels of IL-6 and secondary infection(s)." (PMID 40584180, 2025). "The exclusive inhibition of IL-6 trans-signaling offers a hitherto unique mode of action that may preserve the anti-inflammatory activity of IL-6, such as its contribution to intestinal tissue regeneration and infection defense." (PMID 39857830, 2025). "Interleukin-1β (IL-1β) and interleukin-6 (IL-6) are chemotactic cytokines that amplify inflammation, activate neutrophils and macrophages, promote alveolar bone resorption and febrile responses, and play key roles in infection and tissue injury." (PMID 41354715, 2025). "In comparison to the vehicle group, during the early phase of infection (4 dpi), serum levels of IL-1β (P < 0.0001) and lung tissue levels of IL-1β (P < 0.05) exhibited approximately a twofold increase, while lung tissue levels of IL-6 also doubled (P < 0.01)." (PMID 40475788, 2025). "When the body is stimulated by MP infection, activated immune cells (such as macrophage and monocyte) release interleukin-6 (IL-6), interleukin-1β (IL-1β), and tumor necrosis factor-α (TNF-α), and these inflammatory factors reach the liver through blood circulation." (PMID 40171163, 2025). "Moreover in our study, the infection biomarkers such CRP, IL-6 and procalcitonin, were balanced between both groups, which suggested that the severity of infection was similar." (PMID 39911872, 2025). "Only IL-6 and IL-1RA were significantly higher in Omicron BA.2 virus-infected HNECs compared to D614G, Gamma, and Delta infections (IL-6 D614G vs BA.2 p = 0.0377, p = 0.0093; IL-1RA Delta vs BA.2 p = 0.0174, Gamma vs BA2 p = 0.0063, Delta vs BA.2 p = 0.0065) D614G." (PMID 40295859, 2025). "This divergence underscores the complex role of IL-6 in host defence, which may differ significantly between anatomical compartments and infection types." (PMID 40819633, 2025). "The relationship between IL-6 and zinc in the context of infections is complex." (PMID 40756075, 2025). "LRE11 CFS at 10% + vitamin D had the same outcome than the CFS alone significantly decreased IL-6 production upon infection (p < 0.01), while the co-treatment with vitamin D and 5% LRE11 CFS showed an IL-6 reduction upon infection (p < 0.0001) and also compared to the CFS treatment alone (p < 0.05)." (PMID 40351306, 2025). "As with the IV infection, Tax1bp1-deficiency led to a considerable non-statistically significant decrease in IL-6 production and a substantial decrease in IFN-γ in the serum." (PMID 41171885, 2025).
infection (continued). "P. gingivalis-infection significantly increased IL-6 in young ND-derived cells." (PMID 40581654, 2025). "As microglia and astrocytes are activated to contain infections, and thus, protect neurons from further damage, IL-6 released in response to inflammation could create a positive feedback mechanism contributing to this reactive gliosis." (PMID 40584180, 2025). "We investigated the effects of mPGES-1 inhibitors (MF63 and MK886) on the production of pro-inflammatory cytokines (TNF-α, IL-1β, and IL-6), the anti-inflammatory cytokine IL-10, and the chemokine IL-8 in macrophages infected with E. coli at a multiplicity of infection (MOI) of 5:1." (PMID 40666730, 2025). "In addition, the expression of pro-inflammatory cytokines, such as Il1b, Tnf and Il6, was also reduced in RBP4-deficient mice on day 3 post-infection, indicating a decrease inflammation." (PMID 41144502, 2025). "The absence of TLR2 and TLR4 results in impaired phagocytosis and reduced levels of TNF-α, IL-6, IL-10, and nitric oxide, which could promote a persistent infection." (PMID 41346968, 2025). "HKDM infection with WT bacteria induced IL-6 production at all time points." (PMID 40637600, 2025). "Given the importance of IL-6, we examined its production in the two infection stages." (PMID 40429887, 2025). "Delta‐infected males showed increased pulmonary infiltration of CD163+ “M2” macrophages, Ly6G+ neutrophils, and NKR‐P1C + NK cells during early onset of infection, and elevated lung inflammatory cytokines such as IL‐10, IL‐6, and IP‐10 than Delta‐infected females." (PMID 40686017, 2025). "Both day 0 and day 7 IL-6 levels were positively associated with hospital infections (P = 0.005 and P = 0.01, respectively), while day 3 was not (P = 0.5)." (PMID 40713822, 2025). "IL-6 is a pleiotropic cytokine involved in inflammation, infection, and cancer." (PMID 40529483, 2025). "Age > 60, a clinical factor associated with the TLT subtype, was associated with 57 upregulated genes, including BCR signaling genes, IL6 (related to infection), and IL21R (different from TLT vs. ME), and 141 downregulated genes including EPCAM, AR, WT1, and CD28." (PMID 39866884, 2025). "Elevated IL-6 levels are often correlated with the severity of infection." (PMID 40692679, 2025). "Both infection and vaccination elicit robust Th1/Th17-dominant immune responses and increased cytokine production (IL-6, IFN-γ, TNF-α), which may intensify orbital inflammation, despite similar TRAb positivity rates." (PMID 41509944, 2025). "In addition, the relationship between the kinetics of known stress and infection parameters (cortisol, interleukin 6, C-reactive protein) and skin antioxidant concentration in term and preterm infants needs to be examined." (PMID 40283089, 2025). "However, only a few inflammatory mediators remained elevated at 28 days post-infection in the hippocampus in the B.1.351 model (IL-6) and in the CSF in the AAV model at 7 weeks post-infection (CXCL10, CCL11)." (PMID 39861887, 2025). "We observed a significant positive association between BMI and IL-6, which was independent of the time since infection." (PMID 41323348, 2025). "Downstream, stacking cytokine blockers (e.g., IL-1 or IL-6 inhibitors) with steroids or other immunosuppressants increases serious-infection rates and requires screening and monitoring for hepatitis B reactivation with guideline-concordant antiviral prophylaxis in at-risk patients." (PMID 41458814, 2025). "Infection of the parental visceral VNPAD-30315 cells caused a low level of increase in IL6 transcripts but only at 24 h, not at 72 h." (PMID 41157583, 2025). "Supporting our findings about the relationship between IL-6 and Th-1 cytokines, several studies indicate that IL-6 interferes in the response of MΦs infected with mycobacteria to produce IFNγ, thus limiting the Th1 response’s ability to eradicate the infection." (PMID 41189022, 2025).
infection (continued). "Furthermore, compared with those in the shControl infection group, the levels of IL‐6 and TNF‐α in the cell supernatant from the Poly‐IC with TRIF‐knockdown group were increased." (PMID 40406905, 2025). "As the infection or inflammation progresses, fetal leukocytes begin to infiltrate, resulting in elevated concentrations of pro-inflammatory cytokines such as IL-1β, IL-4, IL-6, and IL-8." (PMID 40640885, 2025). "IL-6 is increased in C57BL/6 infected mice throughout the acute infection." (PMID 40356908, 2025). "Besides analyzing ferroptosis-related protein markers, this cohort study also evaluated traditional biochemical indicators of infection, including IL-1β, IL-6, IL-8, IL-10, CXCL2, and TNF-α." (PMID 40264754, 2025). "IL-6 production can be triggered by infection and various forms of inflammation." (PMID 40063597, 2025). "IL-6 levels in maternal and neonatal blood are known to be related to infection severity." (PMID 39940970, 2025). "Furthermore, the expression of TLR4, IL-1β, IL-6, and IL-10 was up-regulated at 24 h post infection in the common carp (Cyprinus carpio) spleen in response to A. hydrophila." (PMID 40298788, 2025). "The expression levels of IFN-γ, IFN-α, IL-1β, IL-6, and IL-12p40 mRNA were significantly increased, reaching their highest levels at 12 days post-infection (dpi), with fold changes of 18.49-, 28.39-, 36.98-, and 28.98-fold, respectively, before gradually declining thereafter." (PMID 41295722, 2025). "Following infection, the EBOV VP24 protein antagonizes STAT3 to block IL-6-mediated signaling—consistent with IL-6 being one of the key cytokines that activate STAT3 during infections with various viruses (e.g., SARS-CoV-2, respiratory syncytial virus, and IAV)." (PMID 41488475, 2025). "The exact pathogenesis of CD is still unknown, though interleukin-6 (IL-6) is believed to be a potential driving factor, and some cases are closely linked to human herpesvirus-8 (HHV-8) infection." (PMID 41346625, 2025). "Moreover, GzmA also induces IL-6 and IL-8 production in fibroblasts and epithelial cells, helping them to take care of infections by stimulating their immunoregulatory functions." (PMID 41009359, 2025). "In addition, FABP4 inhibition significantly decreased IL-6 secretion 48 h post-infection, suggesting an improved inflammatory state." (PMID 39843629, 2025). "However, under PGRP5-KD circumstances, IL-6 mRNA clearly dropped almost at the time of each infection." (PMID 39888929, 2025). "Indeed, therapeutic targeting of IL-6 requires precise timing, as IL-6 levels rise early in infection, before peak viral clearance." (PMID 40692679, 2025). "IL-6 has long been recognized for its involvement in acute phase response to infection, inflammation, or tissue damage through stimulation of hepatocytes to secrete acute-phase proteins such as C-reactive protein (CRP), a diagnostic marker of inflammation and microbial infection." (PMID 39857830, 2025). "The cell types that secrete IL-6 (neurons, astrocytes, and endothelial cells) are all present in the human cerebral organoids in our model system, making the detection of this cytokine highly likely during neuro-stress and infection." (PMID 40985448, 2025). "Furthermore, genes associated with inflammaging (IFNα, IL1β, NLRP3, IL6, IL1R and p16) and myeloid lineage (RUNX1, Fil1, CD150, PU.1 and GM-CSF) genes that were upregulated by Omicron PsV infection were downregulated by NGO treatment." (PMID 40025168, 2025). "The levels of pro-inflammatory cytokines, such as tumor necrosis factor alpha (TNF-α), interleukin 6 (IL-6), and interleukin 1 beta (IL-1β), which drive chronic inflammation in plasma and lymph nodes, remain elevated from early infection stages and persist even in ART-treated individuals." (PMID 40704918, 2025). "During infection, inflammatory cytokines such as IL-6, IL-8, and CXCL-10 are often elevated." (PMID 40002820, 2025).